EGFR (epidermal growth factor receptor)
Diseases named in the same sentence as EGFR in open-access papers (continued):
Sharing a sentence is not in itself a finding about the gene and the disease.
lung cancer (continued). "Thus, EGFR-mediated tyrosine phosphorylation represents a newly identified mechanism by which the tumor suppressive function of GPRC5A is inactivated in lung cancer." (PMID 25311788, 2014). "Lung cancer has entered an era of personalized therapy with treatment based on histologic subtypes (adenocarcinoma versus squamous) and the presence of molecular markers [epidermal growth factor receptor (EGFR) and anaplastic lymphoma kinase (ALK)]." (PMID 25295226, 2014). "We analyzed patients with lung cancer with nodular GGOs to investigate the correlation between biomarker status and clinicopathological and radiologic characteristics and to determine the roles of ALK rearrangements and EGFR mutations in nGGOs." (PMID 24885886, 2014). "There is a cross-talk between the c-Met and EGFR signaling pathways in lung cancer." (PMID 24884778, 2014). "As a methodological base to identify lung cancer patients who might benefit from EGFR-specific antibodies, we studied the relationship between EGFR-expression on protein level and gene copy numbers assessed by FISH." (PMID 25227424, 2014). "Heat shock protein 90 is a chaperone protein that assists posttranslational folding of several proteins to stabilize and protect them from cellular stresses like heat or hypoxia, including critical proteins in lung cancer such as EGFR, HER2, MET, ALK, and others." (PMID 25505733, 2014). "Importantly, the level of phosphorylation and activity of EGFR appears to correlate negatively with survival in lung cancer patients." (PMID 24456610, 2014). "Importantly, constitutive activation of EGFR or enhanced EGF signaling is frequently found in different types of cancers, especially in lung cancer, where it is associated with cancer initiation, tumor growth/progression, metastasis and poor prognosis." (PMID 24849319, 2014). "Therapeutic approaches against EGF or EGFR represent a promising direction for lung cancer therapy." (PMID 24849319, 2014). "Epidermal growth factor receptor (EGFR) is an important therapeutic target in lung cancer." (PMID 25202368, 2014). "Interestingly, EGFR mutations are typically exclusive with KRAS and BRAF mutations, at least in lung cancer, and tumours exhibiting one of the latter two are relatively insensitive to EGFR inhibitors." (PMID 24643470, 2014). "However, the median PFS of NSCLC patients with EGFR mutation was only 9.5 months on treatment with tyrosine kinase inhibitors (TKIs); The median PFS for patients with locally advanced ALK-positive lung cancer was only 7.7 months with crizotinib treatment." (PMID 25477004, 2014). "RET (rearranged during transfection) fusions are considered to be driver mutations in lung cancer because they are not found in association with changes in EGFR, KRAS, ALK or HER2." (PMID 24722523, 2014). "It is well-known that EGFR signaling is critically involved in lung cancer development." (PMID 24849319, 2014). "Growing evidence supports abnormally activated mTOR to play an important pathogenic role in lung cancer associated with both KRAS and EGFR mutations and may provide a mechanism of resistance to treatment with EGFR inhibitors." (PMID 24593867, 2014). "In summary, we demonstrated novel mechanisms by which hinokitiol, an essential oil extract, acted as a promising anticancer agent to overcome EGFR-TKI resistance in lung cancer cells via inducing DNA damage, autophagy, cell cycle arrest, and senescence in vitro and in vivo." (PMID 25105411, 2014). "In one series, EGFR testing could be performed in 100% of endobronchial biopsy specimens that established a diagnosis of lung cancer." (PMID 25295226, 2014). "Therefore, EGFR endocytosis-related effector or regulator proteins can be used as molecular markers to improve the therapeutic efficacy of gefitinib in lung cancer with wtEGFR." (PMID 24658031, 2014).
lung cancer (continued). "And those light or never-smoking lung cancer patients had a higher ratio of EGFR mutations that had been linked to EGFR-TKI therapy response." (PMID 24643204, 2014). "There are multiple agents in development with enhanced affinity for T790M mutant lung cancer that may spare wild type EGFR, potentially avoiding toxicities like rash and diarrhea." (PMID 25505733, 2014). "Our results in lung cancer cell lines lacking activating EGFR mutations are consistent with these clinical findings, as cells do not undergo apoptosis but rather have growth arrest." (PMID 25501935, 2014). "Overall, results showed that EGF conjugation to nanocarriers could effectively target the EGFR overexpressing lung cancers when administered by inhalation." (PMID 25266303, 2014). "Criteria for acquired resistance to EGFR-TKI in lung cancer." (PMID 25538894, 2014). "However, EGFR endocytosis is the most reasonable target among the RTKs as oncogenic changes from EGFR signaling mostly occur lung cancer compared to those of other RTK signaling." (PMID 24658031, 2014). "Furthermore, miR-224 upregulation enhances radiation sensitivity of medulloblastoma cells, and a 13-gene miRNA signature including increased miR-224 levels would predict good response of lung cancer cells to EGFR inhibitor erlotinib treatment." (PMID 25410592, 2014). "KIF5B-RET is reported in a low percentage of lung cancers and is more frequent in non-smokers, in patients with adenocarcinoma, and exists exclusively with other mutations, such as EGFR, Kras, Braf, ErbB2 or EML4/ALK fusions." (PMID 25047660, 2014). "Our results indicate that targeting HER-2 with T-DM1 may offer a new therapeutic approach in HER-2 over-expressing lung cancers including those resistant to EGFR TKIs." (PMID 24898067, 2014). "EMT has frequently been observed in drug-resistant cancer cells in both preclinical models and clinical samples, including resistance to anti-EGFR therapy in lung cancer, resistance to androgen-deprivation therapy in prostate cancer, and resistance to chemotherapy in breast cancer." (PMID 25379179, 2014). "Gefitinib, erlotinib and afatinib have been approved for EGFR-overexpressing lung cancer." (PMID 24651269, 2014). "Numerous reports have shown that EGFR gene mutations are frequently detected in lung cancer, especially in adenocarcinoma, females, and non-smoking patients." (PMID 24650256, 2014). "Erlotinib, for example, typically is effective on patients with EGFR mutations, but generally does not successfully treat lung cancer patients without malignancy reoccurrence." (PMID 23407898, 2013). "The new generation EGFR-TKI inhibited the growth of lung cancer cells containing the gatekeeper EGFR-T790M mutation, but did not inhibit the growth of cells with Met amplification or HGF overexpression." (PMID 24386407, 2013). "The purpose of this study was to examine whether 2 clinically approved mTOR inhibitors, temsirolimus and everolimus, overcome HGF-dependent resistance to EGFR-TKIs in EGFR mutant lung cancer cells." (PMID 23690929, 2013). "We suggest that protein complexes in cell membranes, including lipid rafts, may serve as novel targets for combination therapies with EGFR and Src Family Kinase inhibitors in lung cancer." (PMID 23866081, 2013). "In the present study, the detection rate of EML4-ALK fusion gene increased from 1.0% (2/202 patients with unselected lung cancer) in the test set to 5.1% (8/158 patients with EGFR and KRAS mutation-negative adenocarcinoma) in the validation set." (PMID 23936355, 2013). "We next evaluated whether mTOR inhibitors would control the growth of EGFR mutant lung cancer cells with HGF-triggered EGFR-TKI-resistance in vivo." (PMID 23690929, 2013).
lung cancer (continued). "Constitutively-active inhibitor-sensitive EGFR mutants are an important mechanism in 10% of nonsmall cell lung cancer (NSCLC) cases, conferring a significant survival benefit when cancer cells dependent on this proliferative signal are deprived via EGFR-inhibition." (PMID 24364026, 2013). "Gefitinib increased cytotoxicity of NK cells to human lung cancer H1975 cells with EGFR L858R + T790M mutations, while not in A549 cells with wild type EGFR." (PMID 23937717, 2013). "However, the relationship of AURKA, EGFR-WT, and mutant EGFR must be further evaluated to identify therapeutic targets for lung cancer patients." (PMID 23520446, 2013). "EGFR mutations could be present in early stage NSCLC, suggesting that it may be possible to detect of lung cancer at more early stages via the molecular testing of mentioned driver mutations in susceptible individuals." (PMID 27234388, 2013). "Accordingly, combinational targeting of STAT3, Akt and EGFR may prevent or reverse drug resistance of EGFR TKI-based therapy in the lung cancers." (PMID 24280348, 2013). "MET is also usually expressed along with EGFR in several human cancers, including lung cancer." (PMID 23407898, 2013). "We performed EGFR TAP in two lung cancer cell lines: PC9 cells, which harbor an exon 19 deletion E746-A750 EGFR mutation and contain five copies of the EGFR gene per cell, and HCC827 cells, which harbor an exon 19 deletion E746-A750 EGFR mutation and contain 35 copies of the EGFR gene per cell." (PMID 24189400, 2013). "In addition, Mig6/EGFR as a predictor of EGFR activity or erlotinib resistance demonstrated a high degree of accuracy in head and neck, bladder and lung cancer cell lines, primary xenografts, and patient samples." (PMID 23935914, 2013). "Our results suggested that gefitinib could enhance the ability of NK cell degradulation to lung cancer cells with EGFR L858R + T790M." (PMID 23937717, 2013). "This phenomenon may not be limited to ESR1 FISH analysis, since similar artifacts were seen also in a case of EGFR-amplified lung cancer." (PMID 24367641, 2013). "Although EGFR mutations are generally found in lung cancer patients who are non-smokers, seven of 23 smokers (30%) achieved SD≥6 months/PR/uPR." (PMID 23435217, 2013). "Our results show that integrin α2β1 and EGFR cooperatively promote higher invasiveness of IR-survived lung cancer cells, mediated in part by the PI3K/Akt signaling pathway, and might serve as alternative targets in combination with radiotherapy." (PMID 23951036, 2013). "EGFR mutations occur more frequently in lung cancer patients who are Asians, females and non-smokers with the histological subtype of adenocarcinoma." (PMID 23879483, 2013). "The purpose of this study was to determine whether bufalin, a major bioactive component of Venenum Bufonis, could reverse HGF-induced resistance to reversible and irreversible EGFR-TKIs in mutant lung cancer cells PC-9, HCC827, and H1975." (PMID 23533466, 2013). "Whereas EGFR mutations tend to occur more frequently in never-smokers with lung cancer, the presence of KRAS mutations cannot be easily predicted based on smoking status alone." (PMID 27234388, 2013). "Taking a collective look at the literature and our results it seems interesting that the lung cancer cell line which did not experience increased cell death with mithramycin (H1975) has an EGFR mutation." (PMID 24367505, 2013). "The role of EGFR inhibition in patients with wild-type EGFR and lung cancer has been debated." (PMID 23800712, 2013). "We will review the state of the art in EGFR-mutant lung cancer." (PMID 24157419, 2013). "In addition, HGF stimulates VEGF production by EGFR mutant lung cancer cells, as well as facilitates angiogenesis, thereby promoting tumor progression." (PMID 23690929, 2013). "On the other hand, EGFR is highly expressed in various cancers, including lung cancer." (PMID 23384026, 2013).
lung cancer (continued). "Similarly, a very recent study in lung cancer cell lines has addressed the miRNA response to EGFR inhibition by shRNA." (PMID 23724959, 2013). "Despite recent successes with molecular targeted therapies for chronic myelogenous leukaemia, ER- or Her2-positive breast cancer, and EGFR-mutated lung cancer, targeted therapies for EOC have not been as encouraging." (PMID 23666744, 2013). "Interestingly, c-Met and epidermal growth factor receptor (EGFR)inhibitors can synergistically inhibit cell proliferation and promote apoptosis in lung cancer." (PMID 23469231, 2013). "The overall therapeutic decision remains a clinical one for a significant proportion of elderly patients with advanced stage lung cancer but no known EGFR mutation status." (PMID 23929397, 2013). "ERBB2 may play a role in protecting EGFR against ubiquitination, and our results suggest strong interactions between EGFR and ERBB2 in these EGFR-mutated lung cancer cells." (PMID 24189400, 2013). "Some pilot studies have reported that intrinsic factors in EGFR-mutant lung cancer cells, such as mutations in T790M, PI3CA, or KRAS and activation of the intracellular Fas/NF-κB signaling pathway, may confer primary resistance to EGFR TKIs." (PMID 24376677, 2013). "Treatment options in lung cancer depend upon the type of cancer, stage of disease, and patient health, and include surgery, radiation therapy, platinum based chemotherapy regimens, and epidermal growth factor receptor (EGFR) tyrosine kinase inhibitors (TKIs)." (PMID 25562729, 2013). "Seike and colleagues reported that EGFR mutations are generally associated with increased miR-21 expression in nonsmoking lung cancer patients, and AMO-mediated miR-21 knockdown sensitized cancer cells to the EGFR-tyrosine kinase inhibitor AG1478." (PMID 24275848, 2013). "Based on the concept that inhibition of PI3K/AKT pathway may effectively overcome HGF-induced resistance to gefitinib, we hypothesized that bufalin could reverse EGFR-TKIs resistance induced by HGF in EGFR mutant lung cancer." (PMID 23533466, 2013). "Surgery, radiation therapy, and chemotherapy using tumor specific targeted agents such as vascular endothelial growth factor (VEGF) inhibitor bevacizumab and epidermal growth factor receptor-tyrosine kinase inhibitors (EGFR TKIs) are the primary tools for treating lung cancer." (PMID 23956990, 2013). "Ectopic expression of miR-7 was able to overcome EGFR TKI resistance in lung cancer cell lines." (PMID 23802096, 2013). "In the present study, we examined whether the clinically approved mTOR inhibitors, temsirolimus and everolimus, circumvent HGF-triggered EGFR-TKI resistance in EGFR mutant lung cancer cells using in vitro and in vivo models, and assessed underlying mechanisms." (PMID 23690929, 2013). "Since the identification of some alterations in the expression of both epidermal growth factor/epidermal growth factor receptor (EGF/EGFR) in lung cancer pathogenesis, several therapeutic targeting agents have been employed for the treatment of lung tumors overexpressing these molecules." (PMID 26317020, 2013). "EGFR gene mutations, KRAS gene mutations, EML4-ALK rearrangements and altered MET signaling are widely recognized alterations that play important roles in both the biological mechanisms and the clinical sensitivity to treatment in lung cancer." (PMID 27234388, 2013). "Our studies showed that bufalin could reverse resistance to reversible and irreversible EGFR-TKIs induced by exogenous HGF in EGFR mutant lung cancer cells by inhibiting the Met/PI3K/Akt pathway and inducing death signaling." (PMID 23533466, 2013). "Furthermore, results from IHC staining with established lung cancer cell lines revealed that increased expression of Nanog and nuclear translocation of β-catenin occurred concomitantly in response to EGFR signaling." (PMID 23648139, 2013).
lung cancer (continued). "To test this hypothesis, we investigated the correlation between plasma pro-inflammatory cytokine levels and clinical outcomes following EGFR-TKI treatment in lung cancer patients." (PMID 23566546, 2013). "The Keap1 mutation was only detected in patients with advanced adenocarcinoma (4.3%) and the completely exclusive status of this mutation and others, including EGFR, Kas, erbB2 and NRF2L2, is likely to improve the selection of personalized therapy for lung cancer." (PMID 24137397, 2013). "The PI3K/AKT/mTOR pathway contributes to the survival of EGFR mutant lung cancer cells." (PMID 23690929, 2013). "Defining mechanisms for constitutive activation of EGFR could elucidate additional targets for therapy of lung cancers." (PMID 23866081, 2013). "The STAT3 activation and the subsequent Akt recovery may be one of the key mechanisms of therapy-induced tumor progression in the lung cancer patients who received EGFR TKI treatment." (PMID 24280348, 2013). "EGFR signaling pathways are involved in the development and progression of lung cancer." (PMID 23874880, 2013). "The targeting of oncogene-addicted cancers such as EGFR-driven lung cancer or ELM4-ALK-driven lung cancer has resulted in major improvements in patient outcomes, yet tumor regression can be short lived in some cases and acquired resistance is nearly always observed." (PMID 24189400, 2013). "On the other hand, while there have also been scattered reports of EGFR mutations among cases of lung squamous-cell carcinoma, a recent report showed that there were no EGFR mutation-positive cases among lung cancer patients with pure squamous cell carcinoma." (PMID 23879483, 2013). "The epidermal growth factor receptor tyrosine kinase inhibitors (EGFR-TKIs), such as gefitinib and erlotinib, have shown promising therapeutic efficacy in nonsmall cell lung cancer (NSCLC) patients harboring epidermal growth factor receptor- (EGFR-) activating mutation." (PMID 23533466, 2013). "Induction of PP2A-dependent necroptosis by FTY720 was also detected in H157 (K-Ras mutant) and H827 (EGFR mutant) human lung cancer cells, in which inhibition of RIPK1 or PP2A using necrostastin or OA and knockdown of RIPK1 or PP2Ac prevented FTY720-mediated cell death compared to controls." (PMID 23180565, 2013). "Thus, HGF treatment restored growth inhibition of epidermal growth factor receptor (EGFR)-mutant lung carcinoma cells by the EGFR tyrosine kinase inhibitor gefitinib and that of BRAF-mutant melanoma cells by the BRAF inhibitors PLX4720 and PLX4032." (PMID 24216702, 2013). "The list of targeted therapies is rapidly expanding, and molecular tests are already mandatory to guide treatment decisions for patients with metastatic colorectal carcinomas with EGFR antibodies, lung carcinomas with EGFR inhibitors and metastatic melanomas with BRAF inhibitors." (PMID 24119386, 2013). "For these reasons, in this work we evaluated the tissue reactivity of ior egf/r3 Mab, the murine counterpart of nimotuzumab, in lung carcinomas as well as, the ability of this Mab to bind the extracellular domain of EGFR inhibiting cell proliferation and inducing apoptosis in a NSCLC cell line." (PMID 26317020, 2013). "Our data presented here for the first time demonstrate that I3C reduces radiosensitivity of lung cancer cells by mediating EGFR expression, indicating that EGFR may be an important target for I3C-mediated radioresistance in lung cancer." (PMID 22814257, 2012). "Alteration of EGFR expression and gene amplification has been reported as between 7 % and 45 % in lung cancer cases, which may also be due to variations in techniques, criteria to determine positivity, and inter-observer variability." (PMID 22537942, 2012). "Therefore, strategies to overcome EGFR TKI resistance remain practical needs in order to prolong survival time of patients with lung cancer." (PMID 23185274, 2012).